FGF23 (fibroblast growth factor 23)
Diseases named in the same sentence as FGF23 in open-access papers (continued):
Sharing a sentence is not in itself a finding about the gene and the disease.
vitamin D deficiency (98 papers, 2012 to 2026). A nutritional condition produced by a deficiency of VITAMIN D in the diet, insufficient production of vitamin D in the skin, inadequate absorption of vitamin D from the diet, or abnormal conversion of vitamin D to its bioactive metabolites. "Although vitamin D deficiency and FGF23-mediated hypophosphatemic disorders sometimes coexist, serum FGF23 levels are elevated in the latter condition." (PMID 40297189, 2025). "After transplantation, the persistence of secondary and tertiary hyperparathyroidism, renal osteodystrophy, relative vitamin D deficiency and high levels of fibroblast growth factor-23 contribute to post-transplant bone disease." (PMID 38339137, 2024). "Recent studies have uncovered a paradoxical finding in CKD, where vitamin D deficiency is accompanied by overexpression of fibroblast growth factor-23 (FGF-23), despite FGF23 levels being regulated by the calcitriol-activated vitamin D receptor (VDR)." (PMID 38732588, 2024). "Our results extend the findings of previous investigations addressing FGF23 and graft loss in those with persistent vitamin D deficiency in KT recipients with higher FGF23 levels." (PMID 37949967, 2023). "The VDR-regulated furin system we outline is also observed in humans, as we found that ergocalciferol treatment in patients with vitamin D deficiency reduces furin activity and FGF23 cleavage." (PMID 37681408, 2023). "As for the effect of vitamin D supplementation on serum FGF23 concentration in individuals with vitamin D deficiency, many questions remain unanswered." (PMID 37047636, 2023). "In summary, CKD, the increase of FGF‐23, and vitamin D deficiency are all associated with the occurrence of SHPT, and they are all associated with CRP." (PMID 37102663, 2023). "Vitamin D deficiency, hyperparathryoidism, and increases in FGF23 and osteopontin predicted mortality (p < 0.05 for all)." (PMID 36819194, 2022). "The nutritional deficit, lower physical inactivity, low sunlight exposure, and elevated amounts of fibroblast growth factor 23 (FGF-23) can cause vitamin D deficiency." (PMID 33801744, 2021). "In this study, we investigated the relationship of vitamin D deficiency with FGF23 and biomarkers of endothelial dysfunction (E-selectin) in North Indian kidney transplant patients." (PMID 30456544, 2019). "In conclusion, this study shows that vitamin D deficiency is associated with markers endothelial dysfunction and increased FGF23 in renal transplant subjects." (PMID 30456544, 2019). "Vitamin D deficiency has been shown to be predictive of cognitive decline in older adults, providing a potential explanation for an association between higher FGF23 levels and dementia." (PMID 30830941, 2019). "Vitamin D deficiency was common in kidney transplant recipients in North India, associated with low FGF23 and high E-selectin." (PMID 30456544, 2019). "Considering the high prevalence of vitamin D deficiency and the association of FGF23 with adverse outcomes, we investigated effects of vitamin D3 supplementation on FGF23 concentrations." (PMID 29602956, 2019). "As another indirect sign of vitamin D deficiency, we observed lower serum concentrations of FGF23 under VDD." (PMID 30038585, 2018). "If the lower serum calcium levels are indeed indicative for either vitamin D deficiency or FGF23 excess, interventions should aim to restore this disorder." (PMID 29581540, 2018). "FGF23 mediated phosphate regulation in HIV-associated vitamin D deficiency remains poorly understood." (PMID 30439968, 2018). "On the other hand, vitamin D deficiency significantly decreased the plasma concentration of FGF-23, as observed in VDD+Nx rats." (PMID 30370270, 2018). "A large number of patients in both study groups had vitamin D deficiency and elevated FGF-23 and renin concentrations." (PMID 30057603, 2018). "In the presence of klotho and FGF23, the diet becomes critically important only during vitamin D deficiency." (PMID 27109615, 2016).
vitamin D deficiency (continued). "Proteinuria however is associated with vitamin D deficiency and therefore a decline in FGF23 would have been expected, giving the observed increase in FGF23 levels seen upon supplementation with activated vitamin D in experimental models." (PMID 22530966, 2012). "A direct effect of FGF23 to suppress ACE2 provides an alternative explanation for the recently proposed associations between vitamin D deficiency, activation of the renin-angiotensin system and regulation of α-Klotho expression." (PMID 22970174, 2012). "Typically, it is associated with disturbances in calcium and phosphorus metabolism, hyperparathyroidism, vitamin D deficiency, and the increase in serum fibroblast growth factor 23 (FGF23) levels (Kidney Disease: Improving Global Outcomes KDIGO CKD-MBD Update Work Group, 2017)." (PMID 40417213, 2025). "However, in the context of CKD-MBD, factors such as hypocalcemia, vitamin D deficiency, dysregulation of the FGF23-Klotho axis, as well as other internal environmental disturbances, can lead to dysfunction of these channels." (PMID 40417213, 2025). "Vitamin D deficiency appears to be secondary to FGF-23 overproduction." (PMID 38732588, 2024). "Therefore, we believe that FGF23 must have influenced the association between vitamin D deficiency and LVH/LVDD in the current study." (PMID 38722953, 2024). "Similarly, vitamin D deficiency amplified the risk of adverse cardiac remodeling observed with elevated FGF23." (PMID 38722953, 2024). "Hyperparathyroidism is common in XLH patients and thought to be the result of stimulation of parathyroid cells by FGF23 and by oral phosphate supplementation but could also be related to vitamin D deficiency." (PMID 38226986, 2024). "Consequently, we suggest that including FGF23 in the current study would provide clearer insights into the association between vitamin D deficiency and LVH/LVDD in CKD patients." (PMID 38722953, 2024). "Besides, most participants also had vitamin D deficiency, which added to a possible reduction in 1,25(OH)2D concentrations due to inhibition of 1-alpha-hydroxylase by FGF23." (PMID 35612845, 2022). "Additionally, VDR activation markedly upregulates FGF23 gene expression and substantially increases circulating levels of FGF23 in healthy subjects with vitamin D deficiency and CKD patients." (PMID 34113631, 2021). "The term CKD-mineral and bone disorder (CKD-MBD) indicates a systemic disorder characterized by abnormal levels of calcium, phosphate, PTH and FGF-23, along with vitamin D deficiency, decreased bone mineral density or altered bone turnover and vascular calcification." (PMID 32486167, 2020). "This syndrome comprises one or a combination of the following conditions: vascular or other soft tissue calcification, vitamin D deficiency, abnormalities in bone turnover, abnormal metabolism of calcium and phosphate, an increase of levels of fibroblast growth factor- 23 (FGF-23) and PTH." (PMID 32192220, 2020). "His severe vitamin D deficiency was in part caused by a previous recommendation to eliminate all vitamin D intake because of his granulomas and hypercalcemia.However, his deficiency was exacerbated by the increased circulating levels of 1,25(OH)2D and FGF‐23." (PMID 31687644, 2019). "However, it is the first study in North Indian kidney transplantation population which evaluates vitamin D deficiency, biomarker of endothelial function and FGF23." (PMID 30456544, 2019). "Since vitamin D deficiency may predispose infectious and cardiovascular diseases, FGF-23 effects on innate immune responses may be due to suppression of 1,25D production." (PMID 29946298, 2018). "This supports the increase in FGF23 after replacement of vitamin D deficiency, which has been demonstrated after substitution with 50000 IU ergocalciferol and the increase in FGF23 observed in an uncontrolled trial of cholecalciferol substitution in women only." (PMID 25166750, 2014).
vitamin D deficiency (continued). "In particular, elevated FGF23 may reflect a higher time-averaged phosphorus burden, vitamin D deficiency, different dose of phosphorus binders, lower adiponectin, and dyslipidemia." (PMID 24747427, 2014). "Biochemical analyses discounted vitamin D-deficiency as an aetiological factor but indicated a perturbation of Ca–P metabolism involving low plasma phosphate and high circulating fibroblast growth factor-23 (FGF23) concentrations." (PMID 22023931, 2012). "However, elevated FGF23 may be associated with poor graft outcomes and vitamin D insufficiency after KT." (PMID 37949967, 2023). "Future studies will investigate the role of FGF23 in stimulating expression of Runx2 and Runx2 target genes and enhancing transcriptional activity of Runx2 leading to increased biogenesis of tumor supportive EMVs that drive the vicious cycle and contribute to vitamin D deficiency." (PMID 28300755, 2017). "Thus, once-weekly TPTD administration might decrease serum phosphate levels via the stimulation of FGF23 when vitamin D actions are insufficient to prevent its decrease, for instance, in the presence of vitamin D insufficiency/deficiency." (PMID 26478225, 2016). "Therapy aims at counteracting consequences of FGF23 excess, i.e. oral phosphorus supplementation with multiple daily intakes to compensate for renal phosphate wasting and active vitamin D analogs (alfacalcidol or calcitriol) to counter the 1,25-diOH-vitamin D deficiency." (PMID 24550322, 2014). "Nowadays, the medical treatment is aimed at counteracting consequences of FGF23 excess, i.e. oral phosphorus supplementation with multiple daily intakes to compensate for renal phosphate wasting and active vitamin D analogs (alfacalcidol or calcitriol) to counter the 1,25-diOH-vitamin D deficiency." (PMID 24550322, 2014). "Several risk factors have been identified, including baseline low serum phosphate, vitamin D deficiency, high cumulative or repeated FCM dosing, and preserved renal function (which permits unopposed phosphaturia in response to FGF23)." (PMID 41362568, 2025). "Patients affected by OP are more prone to develop HF because of vitamin D deficiency, elevation of parathyroid hormone (PTH) plasma levels, and increased Fibroblast Growth Factor 23 (FGF-23) activity." (PMID 39997503, 2025). "The association of vitamin D deficiency and TGFβ1/IL-11/p-MEK/p-ERK-dependent fibrosis was also observed in a genetic mouse model of vitamin D deficiency mimicking some effects of FGF-23 overproduction." (PMID 38732588, 2024). "In the end stage, phosphate overload and vitamin D deficiency down-regulate klotho expression in the kidney, which in turn decreases FGF23 affinity to FGF receptors and results in FGF23 resistance." (PMID 37422767, 2024). "This disorder is associated with the accumulation of phosphorus, elevated parathormone (PTH) and fibroblast growth factor 23 (FGF23) levels and vitamin D deficiency and leads to major complication of CKD." (PMID 34228259, 2022). "Recent experimental and clinical studies have highlighted the crucial role of fibroblast growth factor 23 (FGF23) receptor, Vitamin D deficiency, systolic blood pressure in induction and progression of LVH in CKD patients." (PMID 33187492, 2020). "FGF23 increases in the very early course of CKD21–23, and vitamin D deficiency is also commonly observed in CKD especially among those with proteinuria and diabetes." (PMID 28747700, 2017). "Otherwise, once-weekly TPTD could repeatedly stimulate the secretion of FGF23 that inhibits renal phosphate reabsorption and vitamin D activation and might decrease serum phosphate levels via the stimulation of FGF23, when vitamin D stores are insufficient due to vitamin D insufficiency/deficiency." (PMID 26478225, 2016). "Vitamin D deficiency contributed to the elevation of plasma PTH and decrease of plasma FGF-23 levels as well as for important chronic tubulointerstitial changes." (PMID 25222475, 2014).
vitamin D deficiency (continued). "The clinical manifestations of CKD-MBD include imbalances in blood calcium (Ca) and phosphorus (Pi), vitamin D deficiency, increased levels of parathyroid hormone (PTH) and serum fibroblast growth factor-23 (FGF-23)." (PMID 24669256, 2014). "Increases in the serum levels of FGF23 and PTH are responsible for vitamin D deficiency." (PMID 38541146, 2024). "In patients with CKD, the frequency of vitamin D deficiency would increase with CKD progression, which could be caused by various factors, such as increased fibroblast growth factor 23 level, reduced vitamin D receptor, or the accumulation of uremic toxin." (PMID 38633934, 2024). "Similarly, whereas vitamin D deficiency is prevalent in CKD, our findings demonstrate that the influence of CKD on FGF23 cleavage is dominant over the effects of Vdr–/–, an extreme in vivo model of severe vitamin D deficiency." (PMID 37681408, 2023). "Luckily, serum FGF23 could be measured in our hospital, and the elevated level of it helps us distinguish TIO from other secondary osteoporosis as Fanconi syndrome or vitamin D deficiency." (PMID 37417620, 2023). "Phytate-mediated Ca2+ deficiency promotes vitamin D insufficiency and renal phosphate wasting independent of FGF23 expression." (PMID 32271147, 2020). "On comparing 25 (OH) vitamin D deficient (< 37.5 nmol/L) and non-deficient (≥ 37.5 nmol/L) patients, those with 25 OH vitamin D deficiency had higher E-selectin (p = 0.047) and lower FGF23 (p = 0.013) compared to non-deficient patients." (PMID 30456544, 2019). "Second, elevated fibroblast growth factor 23 (FGF23) levels and vitamin D deficiency may contribute to the development of PPCs." (PMID 28747700, 2017). "Vitamin D deficiency in CKD directly impacts the homeostasis of calcium and phosphate: under physiological conditions, regulatory feedback loops maintain this homeostasis, with vitamin D, the fibroblast growth factor-23 (FGF23), and the parathyroid hormone (PTH) acting as additional regulators." (PMID 35893866, 2022). "Also, obesity associated increased fibroblast growth factor 23 (FGF-23) and resultant vitamin D deficiency could potentiate the risk of vascular calcification." (PMID 28331532, 2017). "Different from normal FGF23 and PTH, serum 25-hydroxyvitamin D was significantly lower in AnkKI/KI mice and vitamin D insufficiency was found in four out of seven CMD patients." (PMID 27784318, 2016). "Further, children with both vitamin D deficiency or with hyperparathyroidism had higher levels of urine NGAL as a measure of proximal tubular injury, higher potassium, osteopontin, and FGF23 compared to children without vitamin D deficiency or hyperparathyroidsm." (PMID 36819194, 2022).
autosomal dominant hypophosphatemic rickets (93 papers, 2007 to 2026). Autosomal dominant hypophosphatemic rickets (ADHR) is a hereditary renal phosphate-wasting disorder characterized by hypophosphatemia, rickets and/or osteomalacia. "Fibroblast growth factor 23 (FGF23) was first reported as the causative gene of autosomal dominant hypophosphatemic rickets in 2000." (PMID 40978851, 2025). "In the year 2000, mutations in the FGF23 gene that render the protein resistant to proteolytic cleavage were identified as the cause of the rare disease autosomal dominant hypophosphatemic rickets (ADHR)." (PMID 40237064, 2025). "FGF23 is a potent phosphate and calcium homeostasis regulator, as underlined by the evidence that FGF23 gene mutations cause autosomal-dominant hypophosphatemic rickets (ADHR)." (PMID 40142640, 2025). "Autosomal dominant hypophosphatemic rickets is due to FGF23 variants, while autosomal recessive hypophosphatemic rickets is due to biallelic variants in DMP1, ENPP1, FAM20C or SLC34A3." (PMID 40533633, 2025). "FGF23 has been identified as a gene associated with autosomal dominant hypophosphatemic rickets (ADHR), which plays an important role in the development of bone diseases." (PMID 39009650, 2024). "FGF23 is a pathogenic gene of autosomal dominant hypophosphatemic rickets, and it is also a circulating factor in tumor-induced osteomalacia." (PMID 39096857, 2024). "Fibroblast growth factor 23 (FGF23) is a bone-derived hormone, identified in the year 2000 as the cause of autosomal dominant hypophosphatemic rickets." (PMID 36821389, 2023). "In inherited diseases, autosomal recessive, X-linked, and autosomal dominant hypophosphatemia are caused by a gene mutation that leads to the abnormal production of FGF-23." (PMID 36615052, 2022). "This cleavage occurs between the arginine residues at positions 176 and 179, and mutations at either of the arginine residues renders FGF23 resistant to proteolytic cleavage, giving rise to autosomal dominant hypophosphatemic rickets (ADHR)." (PMID 35629904, 2022). "The FGF23 gene was first identified in a mutated form in patients with autosomal dominant hypophosphatemic rickets (ADHR)." (PMID 35159314, 2022). "Autosomal dominant hypophosphatemic rickets (ADHR) is an extremely rare form of genetic rickets caused by mutations in the fibroblast growth factor 23 gene." (PMID 34444516, 2021). "FGF-23 was originally identified through a gene mutation in patients with autosomal dominant hypophosphatemic rickets or X-linked hypophosphatemic rickets that results in elevated serum levels of FGF-23." (PMID 33767635, 2021). "This phosphaturic factor was first identified as fibroblast growth factor 23 (FGF23) in 2000 by the autosomal-dominant hypophosphatemic rickets (ADHR) consortium when mutations in FGF23 where found to be causing ADHR." (PMID 33716961, 2021). "Malfunctions in some of these regulatory mechanisms are known to cause bone disorders; mutations of FGF-23, for example, are known to cause autosomal dominant hypophosphatemic rickets (ADHR)." (PMID 30863364, 2019). "Autosomal dominant hypophosphatemic rickets (ADHR) is caused by missense mutations in the FGF23 gene at Arg176 or Arg179, which make the protein resistant to inactivation by cleavage." (PMID 30972027, 2019). "FGF23 was originally identified for its role in phosphate metabolism when mutated FGF23 was found in patients with autosomal dominant hypophosphatemic rickets (ADHR), and FGF23 was identified as the causal agent in tumour-induced osteomalacia (TIO)." (PMID 30808384, 2019). "In the year 2000, gain-of-function mutations in fibroblast growth factor-23 (FGF23) were identified as the genetic cause of autosomal dominant hypophosphatemic rickets (ADHR), an inherited renal phosphate-wasting disease." (PMID 29892265, 2018).